IL1B (interleukin 1 beta)
Diseases named in the same sentence as IL1B in open-access papers (continued):
Sharing a sentence is not in itself a finding about the gene and the disease.
Stroke (continued). "Inflammation plays a pivotal role in the pathogenesis of stroke, with key mediators —specifically IL-1β (neutrophil recruitment), IL-6 (acute-phase amplification), and TNF-α (neuronal apoptosis)— confirmed to drive secondary injury and correlate with ICH severity/prognosis." (PMID 40765613, 2025). "Following a stroke, immune cells, including dendritic cells and macrophages, detect pathogens and damage signals within the gut, thereby activating local immune responses through the secretion of pro-inflammatory cytokines, such as IL-6, IL-1β, and TNF-α." (PMID 40625834, 2025). "The upregulation of Ifi27l2a expression is consistent with increased expression of proinflammatory cytokines such as Il1b, Cst7, and Lyz2, suggesting that Ifi27l2a may be involved in promoting inflammatory responses following stroke." (PMID 40843131, 2025). "Similarly, the IL1β expression was elevated at 6 h as well as 7 days post-stroke induction (p < 0.05)." (PMID 40332314, 2025). "Similarly, in the brain, activated microglia and astrocytes in stroke or neurodegeneration release IL-1β, TNF-α, IL-6, and matrix metalloproteinases that disrupt the blood–brain barrier and kill neurons and damage neural connections." (PMID 41462689, 2025). "Additionally, stroke survivors with increased circulating interleukin (IL)-1β and c-reactive protein (CRP) have higher levels of post-stroke fatigue." (PMID 38802847, 2024). "Interestingly, the levels of circulating IL1-β in clinical studies are varied, with some studies reporting no change while others demonstrated increased levels following stroke." (PMID 38802847, 2024). "Additionally, there was a positive relationship between stroke severity and IL1-β gene expression (r = 0.78, p = 0.003)." (PMID 38802847, 2024). "In addition, JDHXD has an important protective effect on the prognosis of stroke by inhibiting IL-1β and IL-18 produced downstream of pyroptosis." (PMID 39139639, 2024). "In addition to Il6, we also observed downregulation of Il1a and Il1b in male stroke brains, and downregulation of Il1r1 in female stroke brains upon genetic ablation of MMP-3." (PMID 39000490, 2024). "Neutralization of IL-1β after experimental stroke significantly reduced MMP2/9 activity in CCA plaques 7 days after stroke and increased fibrous cap thickness compared with control (isotype IgG) treatment, indicating a causative role of IL-1β in mediating inflammatory plaque degradation." (PMID 39112714, 2024). "Previous work showed that mCRP was deposited in the cortical microvessels of individuals who died from either stroke or AD, and this was concomitant with expression of inflammatory markers, such as CD68 and interleukin-1 beta (IL-1β), and also aquaporin 4, associated with lymphatic Aβ clearance." (PMID 38899254, 2024). "Researchers have proposed an important concept called the “senescence-associated secretory phenotype”, whereby aging brain cells release more proinflammatory signals, such as IL, IL-1α, IL-1β, IL-6, and IL-8, which amplify the inflammatory response after stroke in elderly patients." (PMID 38637850, 2024). "However, patients’ HDL recovered some of its anti-inflammatory effect 1 year after stroke, with a significant improvement in inhibiting IL1β release compared to 7-day samples, albeit less potently than control HDL." (PMID 39746448, 2024). "Our study shows that increased salivary IL1-β gene expression could be a non-invasive biomarker of stroke severity, predictive of future performance of daily activities." (PMID 38802847, 2024). "Interleukin-1β (IL-1β) is not only the core of inflammatory response in the brain after ischemic stroke, but also as a key driver of innate immune memory, which result in chronic post-stroke comorbidities." (PMID 39737165, 2024).
Stroke (continued). "The evaluation of stroke severity in IS patients revealed that the Malat1 expressionsignificantly was lower (2.7±0.51 vs 5±1.3, P=0.001) in patients with high NIHSSscore (>7),while IL-1β was higher in patients with NIHSS 0-6 (65.3±7.7 vs 35.1±2.9, P=0.000)." (PMID 38974129, 2023). "EE also inhibited the expression levels of inflammatory cytokines including TNFα, IL-6, and IL-1β, which might facilitate functional recovery after stroke." (PMID 36819784, 2023). "Stroke incidence leads to the generation of reactive oxygen species (ROS) capable of switching glial cells to an active state and mediating the release of cytokines like tumor necrosis factor-ά, IL-1β, and IL-6 along with BDNF." (PMID 37631018, 2023). "Additionally, an injection of adiponectin (5 μg, 30 min before MCAO and immediately after) was able to significantly down-regulate pro-inflammatory cytokines (i.e., TNF⍺, Il-1β) and NFκB protein levels 24 h post-stroke in rats." (PMID 35625066, 2022). "Furthermore, treatment with isorhamnetin in stroke mice improved the integrity of the blood-brain barrier and reduced the levels of IL-1β, IL-6, and TNF-α in the ischemic cortex." (PMID 36160711, 2022). "Based on these findings, future research should elucidate whether the stroke‐induced signaling through IL‐1β and NLRP3 inflammasome pathway could potentially trigger and exacerbate disturbances in the glucose metabolism in ischemic stroke patients." (PMID 35971650, 2022). "dBET1 markedly reduced inflammation and oxidative stress after stroke, indicated by multiple pro-inflammatory cytokines and chemokines including IL-1β, IL-6, TNF-α, CCL2, CXCL1 and CXCL10, and oxidative damage markers 4-hydroxynonenal (4-HNE) and gp91phox and antioxidative proteins SOD2 and GPx1." (PMID 35761277, 2022). "Inhibiting IL-1β signaling in vivo received an improved result after stroke." (PMID 36204568, 2022). "Specifically, IL-1β appears to be a predictor of post stroke fatigue with researchers suggesting that fatigue after stroke may be due to inflammation-induced sickness behaviour." (PMID 35796976, 2022). "Specifically, the AIM2‐inflammasome activation in myeloid cells and the subsequent increase in IL‐1β levels early after stroke have been shown to promote the activation of monocytes and their expression of the FasL, which ultimately induce T cell apoptosis via a FasL–Fas‐mediated mechanism." (PMID 35971650, 2022). "As evident from our data, RIC therapy alone in diabetic stroke unexpectedly augmented the inflammatory gene expressions significantly as compared to the stroke control group when analyzed for IL-6 (p = 0.0001), IL-1β (p = 0.0002), iCAM-1 (p = 0.030), and iNOS (p = 0.021) at 6 h post-stroke." (PMID 36290774, 2022). "As an antagonist of IL-1β, IL-1Ra treatment has been highly neuroprotective experimentally, while endogenous levels of IL-1Ra have been elucidated to be upregulated and related to adverse outcome after cardiovascular disease and stroke." (PMID 35761288, 2022). "IL-1β/IL-6 increased but IL-12p40 decreased in IRF4 CKO vs. flox mice after stroke." (PMID 35963621, 2022). "L1B (IL‐1β) are the main medium of central and peripheral inflammation after stroke." (PMID 34792838, 2022). "In addition, function recovery of stroke by wasp venom treatment was associated with a decrease in TNF-α, IL-1β, IL-6 and inhibition activated microglia as well as apoptosis." (PMID 35171059, 2022). "As the main members of the IL-1 family, IL-1α and IL-1β play an important role in stroke." (PMID 36685518, 2022). "Similarly, high systemic levels of such pro‐inflammatory cytokines (IL‐6, TNF‐α and IL‐1β) have been directly related to cytokine‐induced sickness behavior after experimental stroke." (PMID 35971650, 2022). "Pro-inflammatory cytokine IL-1β levels up and has been proved to aggravate stroke pathogenesis." (PMID 36204568, 2022).
Stroke (continued). "A number of publications have reported different inflammasomes activation implicated in stroke, such as NLRP1, NLRP3, and AIM2, which contribute to activation of Caspase1 that shears the precursors of IL-1β and IL-18 into their mature forms (cl.IL-1β and cl.IL-18)." (PMID 35690810, 2022). "They demonstrated that their model successfully mimicked the ischaemic response as evidenced by the upregulated mRNA expressions of the key markers for stroke, S100B, IL-1β and MBP and additionally substantiate the role of transient cell-substrate interactions herein." (PMID 35806146, 2022). "Combined with knowledge of decreased IL-1β production, smaller infarct volumes, and improved functional outcome, this information helps to understand how BM cells promote neuroprotection after tMCAo in mice, a potential future stroke therapy." (PMID 33924148, 2021). "Therefore, the American Epilepsy Society (AES) and the National Institute of Neurological Disorders and Stroke (NINDS) identified IL-1β as a potential biomarker of epilepsy." (PMID 33377994, 2021). "Increased caspase 1 and IL-1β in phenotypically modified VSMCs was detected in the aortic roots of VSMCs lineage tracing mice fed high cholesterol diet and in human atherosclerotic plaques from carotid artery disease patients who experienced a stroke." (PMID 35008765, 2021). "IL1-RA expression in the injured CNS is initially downregulated compared to IL-1β, but its exogenous administration can lead to improvements in cognitive deficits, tissue loss and leukocyte recruitment in models of traumatic brain injury (TBI) and stroke." (PMID 33407641, 2021). "Similarly, higher levels of both TNF-α and IL-1β in the serum of stroke patients were found to correlated with poor stroke outcomes one year after stroke." (PMID 34884906, 2021). "Additionally, immunofluorescent staining of GSDMD, caspase‐1, and IL‐1β with Iba‐1 generated another line of evidence for enhanced microglial pyroptosis following stroke, whereas A151 treatment significantly suppressed such an increase." (PMID 32239625, 2020). "A study utilizing oral administration of PLX3397 to silence the CSF1R in rats prior to stroke reported that it exacerbated stroke severity and actually increased the infarct size at 3 days by increasing the production of inflammatory mediators by astrocytes (IL-1b, iNOS, IL-6)." (PMID 32345303, 2020). "In our preclinical stroke model, we have previously shown that IL-1β and TNF are produced by largely segregated populations of microglia and macrophages after experimental stroke in mice, providing evidence of the functional heterogeneity among microglia and macrophages post-stroke." (PMID 32503645, 2020). "Interestingly, antibody-mediated suppression of IL-1β reduces the cerebral infarct size in a mouse stroke model, suggesting potential therapeutic opportunities with targeted agents." (PMID 32125488, 2020). "The IL-1β results of the present rat tMCAO study, though limited to one time point, are to our knowledge the first time that such results have been reported this late out after the acute stroke event in this model." (PMID 33275615, 2020). "Moreover, microglia activation is associated with upregulation of IL-1β and TNF-α, thus aggravating TBI and increasing the risk of stroke." (PMID 32454938, 2020). "IL-1β regulating inflammatory responses as one of the cytokines involved in stroke development, the overexpression of IL-1β could affect the functions of cognition and memory." (PMID 32132924, 2020). "Hence, TNFα and IL-1β plasma level assessment can be useful not only for diagnosis of different stroke types, but also their severity and accompanying metabolic disorders." (PMID 31701356, 2020). "IL-1β, a pro-inflammatory cytokine produced primarily by activated microglia and astrocytes, is one of important inflammatory mediators during neuroinflammation after stroke." (PMID 32782321, 2020).
Stroke (continued). "Elevated levels of IL-1β may be a contributing factor to insulin insensitivity in obese patients and brain dysfunction observed in the diabetic after stroke." (PMID 31174550, 2019). "Separately, reports of a potential neuroprotective role of IL-1β post-stroke must be re-examined." (PMID 31281252, 2019). "The main proinflammatory cytokines in stroke are TNFα, IL-1β, and IL-6." (PMID 31544811, 2019). "In this condition, levels of IL-1β in the spleen were also significantly increased after MCAo in PTX3 KO mice, raising the possibility that in stroke neutrophil infiltration regulated by PTX3 could involve IL-1β." (PMID 31602423, 2019). "Finally, inflammatory factors, such as TNF-α and IL-1β, produced after stroke can activate inflammatory pathways, such as NF-κB, in stem cells, thereby enabling stem cells to acquire stronger immune regulation potential." (PMID 30700305, 2019). "After stroke, the expression of IL-1β, IL-1Ra, and the IL-1 receptors increases." (PMID 31544811, 2019). "In contrast to IL1Ra, IL-1β has detrimental effects in stroke." (PMID 31544811, 2019). "While the role of IL-1β (main released isoform) has been well studied in stroke, the role of the IL-1α isoform remains largely unknown." (PMID 31727174, 2019). "Similar to TNF-α and IL-1β, Il-6 levels are elevated in CSF of severe stroke patients." (PMID 31291966, 2019). "The serum IL-1β level was assessed in all patients on the second day after the stroke." (PMID 31644666, 2019). "ELISA analysis of TNF-α and IL-1β showed significantly higher concentrations of these pro-inflammatory cytokines in ischemic brain tissue of KO mice compared to WT controls at day 7 after stroke (p < 0.001)." (PMID 30777093, 2019). "The knockdown of miR-181a enhanced the production of pro-inflammatory cytokines (TNF-α, IL-6, IL-1β, IL-8), and increased levels of the anti-inflammatory cytokine IL-10 result from miR-181 over-expression in a murine stroke model." (PMID 30953275, 2019). "To confirm this, we compared the mRNA levels of IL-1β from sections of various human brain disorders including Alzheimer’s disease, Parkinson’s disease, stroke, rabies, tuberculous meningitis, cerebral malaria, toxoplasma encephalitis, and cryptococcus meningitis with control brain sections." (PMID 29885667, 2018). "There is increasing evidence that P2Y1R plays a role in astrocytes/macrophages–mediated neuroinflammation, which could lead to positively regulate transcription of inflammatory genes, such as TNF-α, IL-1β following post-stroke cognitive impairment." (PMID 29017492, 2017). "IL-1β does not damage the brain by itself, but it is heavily implicated as exacerbating cell death following a CNS injury such as stroke." (PMID 27557843, 2016). "TNF and IL-1β are produced by both microglia and monocytes after stroke." (PMID 26022493, 2015). "Historically, IL-1β was considered the primary ligand mediating an exaggerated response to ischemic injury however recent research indicates IL-1α also plays a crucial role in post-stroke pathogenesis and that it may proceed IL-1β expression." (PMID 25705177, 2015). "Intrathecal production of IL-1β has been demonstrated in stroke patients." (PMID 25124807, 2014). "Levels of mRNA coding for CD45, TNFα and IL1β were elevated at 7 and 14 d after stroke." (PMID 25341035, 2014). "However, in the sub-acute phase (7 d reperfusion) following stroke, TREM2-KO mice showed a decreased transcription of pro-inflammatory cytokines TNFα, IL-1α and IL-1β, associated with a reduced microglial activity (CD68, Iba1)." (PMID 23301011, 2013). "This means that MCP-1 and IL-1β are key factors of macrophages in stroke lesions." (PMID 23431245, 2013). "Recently, IL-1β has been considered a therapeutic target for stroke." (PMID 23431245, 2013).
Stroke (continued). "Although in this study serum IL-1β levels were too low to be detected, a role for IL-1β in post-stroke depressive symptoms has been confirmed in animal models in which the anhedonia elicited by middle cerebral artery occlusion was attenuated by intracerebrovascular injection of IL-1ra." (PMID 23675319, 2013). "Also in the stroke model, treatment with IL-1β has exacerbated ischemic brain damage while IL-1ra or IL-1 gene-deficient (KO) mice have decreased infarct volumes." (PMID 22483094, 2012). "Furthermore, TNF-α, IL-1β, IL-1α, and Cox-2 are well-studied cytokines related to inflammatory responses in stroke, and both appear to exacerbate ischemic damage." (PMID 22719787, 2012). "In addition to these physiological conditions in SHRSP, IL-1β administration slightly increased the incidence of stroke in SHR and significantly accelerated the onset of stroke in SHRSP." (PMID 23326018, 2012). "Exogenous administration of IL1β has been shown to exacerbate ischemic damage, whereas administration of an endogenous IL-1β receptor antagonist or a neutralizing antibody reduced brain damage and edema when administered before a stroke in rats." (PMID 23209732, 2012). "At 4 weeks of age (before stroke onset), the plasma level of IL-1β was significantly higher in SHRSP (153.0 ± 49.7 pg/ml) than in Wistar Kyoto rats (WKY) (7.7 ± 3.4 pg/ml, P < 0.001 versus SHRSP) or spontaneously hypertensive rats (SHR) (28.0 ± 9.1 pg/ml, P < 0.001 versus SHRSP) (n = 6 per strain)." (PMID 23326018, 2012). "More studies are needed to characterize the role of the IL-1β signal in stroke onset in humans." (PMID 23326018, 2012). "In addition, continuous administration of IL-1β (2 μg/day) using an osmotic pump slightly increased the incidence of stroke in SHR (P = 0.046) and significantly accelerated the onset of stroke in SHRSP (P = 0.006) compared to each control (n = 10 per group)." (PMID 23326018, 2012). "Intracerebroventricular or stereotaxic striatal injection of exogenous IL-1β exacerbated stroke-induced damage in young animals, and conversely, injury was reduced after the IL-1β antagonist, IL-1ra, was injected either locally into the striatum or into an intracerebral ventricle." (PMID 22707991, 2012). "More studies are needed to characterize the role of the IL-1β signal in stroke onset, and to confirm if this signal might be a therapeutic target for stroke in humans." (PMID 23326018, 2012). "Therefore, the goal of the present study was to clarify the role of inflammation, especially IL-1β, in the onset of stroke in SHRSP." (PMID 23326018, 2012). "However, the number of rats was limited, and additional experiments are needed to ensure the inverse correlation between plasma IL-1β level and the day of stroke onset." (PMID 23326018, 2012). "The Administration of anti-IL-1β antibody slightly affected the onset of stroke, but it seems that higher doses may be needed to see a greater effect." (PMID 23326018, 2012). "It seems that dietary restriction delayed the onset of stroke via a decrease in plasma IL-1β level." (PMID 23326018, 2012). "IL-1β may be a more important target for prevention or treatment of stroke when compared with IL-6 and TNF-α." (PMID 23326018, 2012). "In stroke patients, increased cerebrospinal fluid and/or circulating IL-1β, IL-6, IL-10, and CXCL-1 (CINC-1/IL-8), monocyte chemoattractant protein-1, and TNF-α concentrations have been reported, and IL-6 in particular identified as a predictor of stroke outcome." (PMID 21714902, 2011). "In this study, we analyzed whether the altered expression of IL-6, IL-1β and G-CSF in MCP-1-deficient mice has an influence on the post-stroke migration of neutrophil granulocytes and T-cells." (PMID 22031820, 2011). "The increases in ICAM-1 and VCAM-1 after stroke are influenced by IL-1β and TNF-α." (PMID 21040547, 2010).